TXNL4A (thioredoxin like 4A)
Description:
Plays a role in pre-mRNA splicing as component of the U5 snRNP and U4/U6-U5 tri-snRNP complexes that are involved in spliceosome assembly, and as component of the precatalytic spliceosome (spliceosome B complex).
Synonyms: DIM1; TXNL4; U5-15kD; HsT161; DIB1; SNRNP15; BMKS
Tractability: Small molecule: a structure with a bound ligand is known; it has a binding pocket of medium quality. PROTAC: ubiquitination databases record sites on it; its protein half-life has been measured.
Gene: Protein-coding gene on chromosome 18 (79,970,813 to 80,033,949, reverse strand). Ensembl gene ENSG00000141759.
Subcellular location: Nucleus
Subcellular location (Human Protein Atlas): Nucleoplasm; Cytosol
Pathways (Reactome):
Metabolism of RNA: mRNA Splicing - Major Pathway; mRNA Splicing - Minor Pathway
Disease: Dengue Virus-Host Interactions
Gene Ontology:
Molecular function: protein binding
Biological process: mRNA splicing, via spliceosome; RNA splicing, via transesterification reactions; spliceosomal complex assembly; spliceosomal snRNP assembly
Cellular component: nucleoplasm; nucleus; precatalytic spliceosome; spliceosomal complex; U2-type precatalytic spliceosome; U4/U6 x U5 tri-snRNP complex; U5 snRNP
Genetic constraint (gnomAD): Loss-of-function variants: 16 observed, 12.23 expected, observed/expected ratio (o/e) 1.31, 90% interval 0.88 to 1.85. The upper end of that interval is the gene's LOEUF score, 1.85, which puts it in group 6 of 6, group 1 being the genes least tolerant of losing a copy. Missense variants: 72 observed, 173.7 expected, observed/expected ratio (o/e) 0.41, 90% interval 0.34 to 0.5. Synonymous variants: 81 observed, 67.81 expected, observed/expected ratio (o/e) 1.19, 90% interval 1 to 1.44.
Gene-disease validity (ClinGen):
ClinGen rates the evidence that TXNL4A causes each of these diseases.
choanal atresia-hearing loss-cardiac defects-craniofacial dysmorphism syndrome (autosomal recessive): Definitive.
Homologues: Orthologues: chimpanzee TXNL4A (100% identical), guinea pig TXNL4A (100% identical), macaque TXNL4A (100% identical), mouse Txnl4a (100% identical), dog TXNL4A (99% identical), pig TXNL4A (99% identical), tropical clawed frog txnl4a (98% identical), zebrafish txnl4a (97% identical), Drosophila melanogaster Dim1 (96% identical), Caenorhabditis elegans dib-1 (87% identical), rabbit TXNL4A (63% identical). Paralogues in human: TXNL4B (37% identical).
Diseases named in the same sentence as TXNL4A in open-access papers:
TXNL4A is named in the same sentence as 20 diseases in open-access papers, as found by Europe PMC text mining. Sharing a sentence is not in itself a finding about the gene and the disease. The quoted sentences say what the papers report.
Burn-McKeown syndrome (8 papers, 2017 to 2024). "TXNL4A is a component of the U5 small ribonucleoprotein particle, which is involved in pre-mRNA splicing and is associated with Burn-McKeown syndrome." (PMID 38552632, 2024). "The craniofacial developmental disorder Burn-McKeown Syndrome (BMKS) is caused by biallelic variants in the pre-messenger RNA splicing factor gene TXNL4A/DIB1." (PMID 32735620, 2020). "Interestingly, one downregulated gene in the EFTUD2-knockdown cell line was TXNL4A, the causative gene in Burn–McKeown Syndrome and another U5 snRNP protein." (PMID 31304552, 2019). "Two of these disorders – mandibulofacial dysostosis Guion-Almeida type (MFDGA) and Burn-McKeown syndrome (BMKS) – are caused by variants in U5 snRNP proteins, EFTUD2 and TXNL4A, respectively." (PMID 33584830, 2021). "This phenomenon, first described in the context of thrombocytopenia-absent radius (TAR) syndrome, has only rarely been invoked since, e.g., SNORD118-related cerebral microangiopathy leukoencephalopathy with calcifications and cysts, and TXNL4A-related Burn-McKeown syndrome." (PMID 32552793, 2020).
retinitis pigmentosa (2 papers, 2021 to 2025). Retinitis pigmentosa (RP) is an inherited retinal dystrophy leading to progressive loss of the photoreceptors and retinal pigment epithelium and resulting in blindness usually after several decades. "Variants in TXNL4A and EFTUD2 manifest in craniofacial malformations while variants in PRPF8 and SNRNP200 manifest in retinitis pigmentosa." (PMID 40264708, 2025).
choanal atresia (1 paper, 2017). Choanal atresia (CA) is a congenital anomaly of the posterior nasal airway characterized by the obstruction of one (unilateral) or both (bilateral) choanal aperture(s), with clinical manifestations ranging from acute respiratory distress to chronic nasal obstruction. "Subsequently, we tested a cohort of 19 individuals with (mild) features of BMKS and 17 individuals with isolated choanal atresia for causative variants in TXNL4A by dideoxy-sequence analysis." (PMID 28905882, 2017). "Hence, we identified causative recessive variants in TXNL4A in two individuals with BMKS as well as in three individuals (from two families) with isolated choanal atresia." (PMID 28905882, 2017).
hepatocellular carcinoma (1 paper, 2023). A malignant tumor that arises from hepatocytes. "The relationship between TXNL4A and clinical features of hepatocellular carcinoma." (PMID 37305572, 2023). "TXNL4A is an independent prognostic factor for hepatocellular carcinoma." (PMID 37305572, 2023).
metabolic syndrome (1 paper, 2025). A cluster of metabolic risk factors for CARDIOVASCULAR DISEASES and TYPE 2 DIABETES MELLITUS. "Of the 22 female-specific MDD/metabolic syndrome pleiotropic regions, possible causal risk loci mapped to multiple genes (GPC6, SHISA9, RP11-154H12.3, KCNG2, TXNL4A, RBFA and ADNP2)." (PMID 40858613, 2025).
pancreatic cancer (1 paper, 2023). "TXNL4A is involved in the immune infiltration of pancreatic cancer; therefore, it was hypothesized that TXNL4A might influence the immune infiltration of HCC." (PMID 37305572, 2023).
retinal degeneration (1 paper, 2019). Degeneration of the retina. "For example, why variants in the U5 snRNP genes PRPF6, PRPF8 and SNRNP200 are associated with retinal degeneration in adRP, while variants in the U5 snRNP genes EFTUD2 and TXNL4A are linked to craniofacial disorders, is not understood." (PMID 31304552, 2019).
undifferentiated carcinoma (1 paper, 2023). A usually aggressive malignant epithelial neoplasm composed of atypical cells which do not display evidence of glandular, squamous, or transitional cell differentiation. "The results revealed that the group with high TXNL4A expression exhibited increased docetaxel tolerance, embryonic stem cells, ROBO receptor signaling pathway dysregulation, tumor invasion, undifferentiated carcinoma, DNA damage, replication, and dysregulation of other pathways." (PMID 37305572, 2023).
cancer (3 papers, 2021 to 2023). A tumor composed of atypical neoplastic, often pleomorphic cells that invade other tissues. "Furthermore, GSEA revealed that genes in the group with high TXNL4A expression were highly enriched in pathways of stem cells and undifferentiated cancers." (PMID 37305572, 2023). "Overlap of essential E‐boxes for four cancer cell lines revealed only three (1%) common E‐boxes: chr1_BS1363_CACAATG with neighbor genes MECR and PTPRU, chr11_BS79_CGCGTG localized near RPLP2 and PIDD1, and chr18_BS691_CATGTG adjacent to RBFA and TXNL4A." (PMID 37519063, 2023). "Since that TXNL4A and SLC25A39 were rarely reported in cancer, we did not discuss them in-depth." (PMID 35096017, 2021).
tumor (1 paper, 2023). "The analyses of differential gene expression in HCC using R resulted in high TXNL4A expression in the tumor samples The same results were replicated in the GSE64041 and GSE39791 datasets." (PMID 37305572, 2023). "The enrichment analyses also revealed similar results, and the genes in the group with high TXNL4A expression were enriched in tumor invasion-related pathways." (PMID 37305572, 2023).
TXNL4A also shares sentences with these, for which no sentence is quoted: Cerebro-costo-mandibular syndrome (1 paper); craniofacial microsomia (1); fungal infections (1); Immunodeficiency (1); infection (1); Leukoencephalopathy (1); mandibulofacial dysostosis (1); mandibulofacial dysostosis Guion-Almeida type (1); microcephaly (1); neuropathy (1).